LINC01579 (long independently transcribed non-coding RNA 1579)
Gene: Long non-coding RNA gene on chromosome 15 (93,718,542 to 94,070,898, reverse strand). Ensembl gene ENSG00000258754.
Diseases named in the same sentence as LINC01579 in open-access papers:
LINC01579 is named in the same sentence as 7 diseases in open-access papers, as found by Europe PMC text mining. Sharing a sentence is not in itself a finding about the gene and the disease. The quoted sentences say what the papers report.
glioblastoma (2 papers, 2022 to 2025). The most malignant astrocytic tumor (WHO grade IV). "LINC01579 has been reported in uterine corpus endometrial carcinoma, gliomas, glioblastoma and Hirschsprung's disease, with only one study related to GC specifically mentioning gastric adenocarcinoma." (PMID 39855898, 2025). "The functional role of LINC01579 in glioblastoma (GBM) has been elucidated in a recent study." (PMID 39855898, 2025).
tumor (2 papers, 2022 to 2025). "Additionally, these articles consistently emphasise the potential role of LINC01579 in tumour proliferation and metastasis, further validating our hypothesis that LINC01579 promotes tumour invasion and migration." (PMID 39855898, 2025). "To shed light on the potential involvement of LINC01579 in the malignant progression of GC, we directed our attention towards the TME, as senescence has been shown to influence TME and contribute to tumour progression." (PMID 39855898, 2025).
cancer (1 paper, 2025). A tumor composed of atypical neoplastic, often pleomorphic cells that invade other tissues. "Following a comprehensive exploration of the mechanisms through which LINC01579 functions in cancer, we anticipate that it will play a crucial role in risk stratification models, thereby enhancing clinical decision‐making as the population ages." (PMID 39855898, 2025).
LINC01579 also shares sentences with these, for which no sentence is quoted: gastric adenocarcinoma (1 paper); glioma (1); Hirschsprung disease (1); uterine corpus endometrial carcinoma (1).